ITGB3 (integrin subunit beta 3)
Diseases named in the same sentence as ITGB3 in open-access papers (continued):
Sharing a sentence is not in itself a finding about the gene and the disease.
tumor (continued). "These expression alterations in PLCL1, PLCL2 and ITGB3 could could potentially influence tumor development and tumor progression." (PMID 40457272, 2025). "This stabilization sustains active integrin signaling pathways that drive oncogenic processes including proliferation, migration, and invasion - a finding consistent with previous reports of ITGB3 stabilization promoting tumor aggressiveness and therapy resistance across multiple cancer types." (PMID 41467954, 2025). "Notably, SERPINA1 overexpression markedly enhanced tumor growth while concurrently increasing ITGB3 expression." (PMID 41467954, 2025). "ITGB3 (integrin β3) is a cell-surface adhesion receptor involved in tumor progression." (PMID 41423632, 2025). "Conversely, SERPINA1 knockdown elicited opposing trends, indicating that SERPINA1 may promote tumor progression by modulating ITGB3." (PMID 41467954, 2025). "ITGB3 influences tumor immunity through both the innate and adaptive immune systems." (PMID 38183097, 2024). "ITGB3 is crucial for tumor invasion, neovascularization, and inflammation." (PMID 39239559, 2024). "When comparing the ITGB3‐KO group and the 143B group, the tumor weights were decreased, and tumor volumes were diminished, which indicated that ITGB3 knockout could suppress tumor growth in vivo." (PMID 36772869, 2023). "ITGB3, as an extensivelystudied member of the integrin family,plays critical and diverse roles in the progression of malignant tumorsand the reprograming of the tumor microenvironment." (PMID 37555842, 2023). "Crosstalk between NRP-1, ITGB3 and FAK was also found earlier in a mouse model, where the suppression of ITGB3 was associated with am NRP-1-dependent change in focal adhesion remodeling in endothelial cells and reduced tumor angiogenesis." (PMID 37175499, 2023). "In addition, ITGB3 had a positive correlation with cisplatin resistance in cells and tumor xenografts in mice." (PMID 36772869, 2023). "By analyzing the BBCancer 25, a blood-based biomarkers of cancers database, we found that the expression level of integrin β3 (ITGB3) was significantly increased in the circulating tumor cells, blood, and EVs from tumor patients than in those from normal controls." (PMID 36263165, 2022). "The miRNA let-7c, a member of the let-7 family, prevents migration and invasion of NSCLC cells by degrading oncogene ITGB3 and could be used as a tumor suppressor in this type of cancer." (PMID 36011391, 2022). "The ITGB3 interacts with integrin αIIb or αV forming integrin αIIbβ3 or αVβ3, with αIIbβ3 predominantly expressed in platelet while αVβ3 predominantly expressed in endothelial cells or tumor cells." (PMID 36130933, 2022). "As ferroptosis is an iron-dependent cell death process driven by the accumulation of lipid ROS, and is also a critical regulator of tumor growth 29, 30, we first tested the intratumoral ROS levels and found that both P-EVs treatment and ITGB3 overexpression reduced the ROS levels in NPC cells." (PMID 36263165, 2022). "Therefore, ITGB3/AKT/β-catenin axis is downregulated by MIIP to suppress tumor angiogenesis and EMT." (PMID 36130933, 2022). "The positive correlation between HOXB5 expression and its target genes CXCR4 and ITGB3 in human CRC cell lines led us to explore whether it also existed in primary tumor tissues." (PMID 33456563, 2021). "As a member of integrin family, ITGB3, also known as CD61 or GPIIIA, could respond to the stromal and immune microenvironment and promote cellular senescence in many types of tumor." (PMID 34805144, 2021). "Additionally, ITGB3 expression is increased during oxidative stress, which further implicates its involvement in the tumor microenvironment (TME)." (PMID 32934781, 2020). "FAM225A could regulate ITGB3 expression by sponging miR-590-3p and miR-1275 and resulted in tumorigenesis and metastasis, indicating its oncogenic role in tumor development." (PMID 33245102, 2020).
tumor (continued). "EDN1, ITGB3, and F3 have been implicated in tumor progression, but they have not been well studied with respect to DS." (PMID 32934781, 2020). "Lower mRNA expression of SEMA3B, SEMA3D, SEMA3G, and PLXNA2 or higher mRNA expression of SEMA3F, NRP1, ITGB3, ITGA5, and VEGFA genes were detected in the older patient group and associated with the higher tumor grade, wild-type status of IDH, and lower rate of survival time (p < 0.05)." (PMID 33036421, 2020). "Among the tumor specimens with IDH mutation, mRNA levels of SEMA3B, SEMA3C, SEMA3D, SEMA3G, NRP2, PLXNA2, and CDH1 were significantly higher (p < 0.05), while SEMA3F, NRP1, ITGB3, ITGA5, and VEGFA genes were under-expressed (p < 0.05)." (PMID 33036421, 2020). "Furthermore, the ß3 integrin (ITGB3) founded exclusively in exosomes isolated from RBVS cells exerts several crucial roles in malignant tumor progression, such as metabolic reprogramming, maintenance of a stem-like phenotype and drug resistant acquisition." (PMID 32545553, 2020). "In order to determine if the observed reduced tumor volume in the Cal+Cur group was related to differences in the intratumor vessel network, microvessel count was performed using the integrin subunit β (Itgb3) as a marker of activated endothelium." (PMID 31698751, 2019). "Moreover, RET-induced cell migration requires integrins, and β3 integrin (Itgb3) expression correlates with RET-mediated invasion in a tumor xenograft model." (PMID 31015297, 2019). "In this respect, our results suggest that highly hypoxic tumours may be more responsive to ITGB3 therapy." (PMID 29383126, 2017). "Functional inhibition of ITGB3 suppresses neovascularisation, tumour growth and metastasis, suggesting that αvβ3 integrin may be a critical modulator of pathological angiogenesis." (PMID 29383126, 2017). "Finally, based on other reports, the phenotypic transition of TGF-beta and the enhancement of tumor invasion and metastasis are coincided with the upregulation of ITGB3." (PMID 27374079, 2016). "Therefore, miR-192-mediated ITGB3 (especially ITGAVB3) plays an important role in tumor-induced angiogenesis, which is essential for metastatic colonization and growth." (PMID 26506238, 2015). "Furthermore, β3 and αvβ3 integrin knockout mice exhibit enhanced pathological angiogenesis of implanted tumours while ITGB3 over-expressing models demonstrate small new vessels deficient in pericytes." (PMID 25807374, 2015). "Concerning ITGB3, an evaluation in the reverse order, where the patients are classified depending on the tumours' ITGB3 expression, could determine if it is possible to distinguish patients who will respond to standard treatment from those who will not." (PMID 19775429, 2009). "The expression of ITGB3 in tumours from survivors in our study may indicate that these tumour cells still retain normal cell properties, and are therefore less aggressive." (PMID 19775429, 2009). "Integrin beta 3 (ITGB3) was more expressed in tumours from survivors in our previous studies." (PMID 19775429, 2009). "Interestingly, integrin β3, the ITGB3 gene product, and its functional heterodimer integrin αvβ3 have also been reported to drive tumor initiation, drug resistance, and metastasis, similarly to STAT3,9–11 suggesting an important JAK/STAT3/integrin β3 signaling axis in PDAC." (PMID 40701148, 2025). "Moreover, other genes such as TLR4, CD4, COL3A1, and ITGB3 are also of great research value, and whether other genes are also involved in the regulation of tumor bone metastases will be investigated in the later studies." (PMID 37007939, 2023). "Thus, we selected a variety of myeloid tumor cell lines to evaluate ITGB3 transcription levels." (PMID 34738870, 2021).
tumor (continued). "This might lead to an upregulation of ITGB3 in miliary ascites tumor cells." (PMID 25991672, 2015). "In addition, significant differences of ITGB3 expression were also detected when tumours were divided according to treatment, with p = 0.05 for paclitaxel and carboplatin treated patients and p = 0.04 for farmorubicine-, carboplatin-, and cyclophosphamide-treated patients." (PMID 19775429, 2009). "The immunohistochemical staining results of the tumor tissue showed that the ratio of PLAT-, TNC- and ITGB3-positive cells decreased in the ADI combined with the gefitinib group." (PMID 39754146, 2025). "M2-polarized HMC3 microglia promoted tumor angiogenesis by releasing exosomal circKIF18A, and circKIF18A bound to its target gene FOXC2 that upregulated ITGB3, CXCR4, and DLL4 expressions and activated PI3K/AKT signaling." (PMID 39781357, 2025). "Three calpain substrates, ITGB1, ITGB3, and ITGB7, were subsequently selected for further study on the basis of their importance in tumor invasion and metastasis as well as the occurrence of missense mutations within the calpain cleavage site." (PMID 40362482, 2025). "The levels of ITGAV, ITGB3 and ITGB5 were significantly higher in GBM samples than in non-tumor specimens." (PMID 40281508, 2025). "ITGB3 plays a critical role in Trastuzumab resistance through the modulation of TGF-β signalling, migration, and contributing to tumour heterogeneity." (PMID 39857240, 2024). "ADAM12, when interacting with its integrin substrates, exhibited an inverse relationship with tumor growth, whereas ADAM15’s interaction with integrin beta 3 (ITGB3) was positively correlated with tumor growth." (PMID 39519201, 2024). "We identified three tumor suppressor miRNAs (miR-34a, miR-124, and miR-1271) that target three adhesion molecules (L1 Cell Adhesion Molecule (L1CAM), Integrin Subunit Beta 3 (ITGB3), Catenin Delta 1 (CTNND1))." (PMID 34298609, 2021). "Many surface markers, including CD106 (Vcam1), CD51 (Itgav) and CD61 (Itgb3), are heterogeneously expressed in the mesenchymal YFP+ EpCAM– population of tumor cells in more than 75% of tested tumors." (PMID 34072345, 2021). "However, the modulation of these genes allows speculating that the ITGB3 knockdown led to a decreased cellular energy metabolism, to reduced tumor growth, impaired possibilities for cytokinesis and migration, as well as to decreased vesicle trafficking (endosome and exosome formation)." (PMID 33083904, 2021). "Integrin β3 (ITGB3) belongs to a family of transmembrane proteins that integrate the ECM processes and participates in reprogramming tumor metabolism." (PMID 34039961, 2021). "The results showed that ITGB1 (4/10), ITGB3 (6/10), ITGB5 (6/10), and ITGB6 (5/10) protein levels were increased in tumour tissues compared to adjacent tissues." (PMID 34709754, 2021). "However, some studies have reported higher expression of ITGB3 or ITGAV negatively associate with prognosis and invasion, suggesting they may be tumor suppressors in OC." (PMID 32765584, 2020). "In contrast, GANT58 reduced expression of ITGB3, GLI2, and PTHRP in tumor cells cultured on both 2D films and bone-like 3D scaffolds, which highlights the potential of Gli2 inhibitors for blocking TIBD." (PMID 32967150, 2020). "Consistent with our previous study using 2D films, expression of ITGB3, GLI2, and PTHRP by tumor cells cultured on 3D scaffolds increased with increasing substrate modulus due to interactions between integrins and growth factors." (PMID 32967150, 2020). "Results show that leptin signaling increases the expression of tumor progression and chemoresistance-related genes (ABCB1, WNT4, ADHFE1, TBC1D3, LL22NC03, RDH5, ITGB3) in TNBC cells." (PMID 32471192, 2020). "In relation to the malignancy grade of the tumor, mRNA levels of SEMA3B, SEMA3C, SEMA3D, SEMA3G, PLXNA2, and CDH1 decreased while mRNA levels of SEMA3F, NRP1, ITGB3, ITGA5, and VEGFA increased with the increase of the tumor malignancy (p < 0.05)." (PMID 33036421, 2020).
tumor (continued). "To have better insights into the PAX8-ITGB3 regulatory network, we performed a putative gene network analysis involving ITGB3 as a mediator of PAX8 in cell–cell interaction (contact inhibition) and cellular adhesion (tumor growth)." (PMID 31832016, 2019). "One of the other targets of miR-140-3p is ITGB3 which cooperates with EGFR as a complex and is also a key factor in tumour cell adhesion and tumour angiogenesis." (PMID 30559931, 2018). "MiR-30a has also been demonstrated to inhibit several critical oncogenes, such as Eya2, ITGB3, or UBE3C, and suppress tumor growth, cell migration and invasion." (PMID 29162923, 2017). "In validation by real-time PCR, four genes (COL4A2, HSPB1, ITGB3, and MAP1A) demonstrated significantly lower expression in tumor-adjacent stroma compared to normal stroma (p value ≤ 0.05)." (PMID 26158290, 2015). "The results based on t test indicate that COL4A2, HSPB1, ITGB3, and MAP1A were significantly less expressed in tumor adjacent stroma in comparison with normal stroma (p values < 0.05)." (PMID 26158290, 2015). "Four genes (COL4A2, HSPB1, ITGB3, and MAP1A) were significantly less expressed in tumor adjacent stroma in comparison with normal stroma (p values < 0.05)." (PMID 26158290, 2015). "From the Human Tumor Metastasis RT-PCR array with ATAD2 siRNA-treated cells, we identified APC, ITGB3, FXYD5, ITGA7 and CTNNA1 (α-catenin), which are related to cell adhesion; among these, the expression of APC and CTNNA1 changed by at least 3-fold." (PMID 24552534, 2014). "Four tumor-related genes were found to be expressed: Phosphatase and tensin homolog (PTEN), a well-known tumor suppressor; c-myc, an oncogene; ITGB3, an adhesion molecule; and IFN-β, a defense factor." (PMID 24926371, 2014). "The expression of CLU, ITGB3, CAPG, and PRAME was investigated to study differences in expression levels between tumours from survivors and tumours from deceased patients." (PMID 19775429, 2009). "The proteins CLU, ITGB3, CAPG, and PRAME were examined with western blot for semiquantitative measurements of each protein in 98 tumours." (PMID 19775429, 2009). "Notably, RARγ peaks were highly enriched near genes involved in cell surface signaling and adhesion, including SERPINE1, ITGB3, ITGA6, and COL4A2, which are known to control both epithelial plasticity and tumor progression." (PMID 41274504, 2025). "The COGS model includes genes such as AP1M2, PLCL1, PLCL2, ITGB3 and BSPRY, whose altered expression could contribute to tumorigenesis and tumor progression." (PMID 40457272, 2025). "ITGB3 expression in the ITGB3-NC + IR group was greater than that in the ITGB3-NC + non-IR group, and all ITGB3-KD groups exhibited low ITGB3 expression, suggesting stable differential expression of ITGB3 in the subcutaneous tumor model." (PMID 40410897, 2025). "In contrast, ITGB3 and ITGA5 — which have been associated to high tumor stages in patients — are not upregulated upon liver metastasis formation in vivo." (PMID 38775153, 2024). "Within miR-18a/low tumours, there was a significantly negative correlation between ITGB3 and miR-18a (Pearson’s correlation co-efficient: −0.42, p = 0.02)." (PMID 38786043, 2024). "In a mouse model lacking ITGB3, studies have found increased M2 macrophages promoting tumor growth, decreased CD8+ T cells, and weakened immune responses." (PMID 39239559, 2024). "The expression of ITGAV, ITGB3, and ITGB5 in EwS was comparable to other tumor entities." (PMID 38318175, 2024). "To understand the molecular mechanism through which integrin β3 regulated cell invasion, we performed Western blot to detect the protein levels of the tumor cell invasiveness inducers, MMP2 and MMP9 (Supplementary Fig5A, 5C), in ITGB3 interfered cells and control cells." (PMID 36944577, 2023). "More importantly, our data for the first time indicated the existence of MIIP in the CM of tumor cells, indicating MIIP could be secreted by the cells and function as a ligand of ITGB3." (PMID 36130933, 2022).
tumor (continued). "The noncovalently-bound integrin subunits αv (Itgav) and Itgb3, namely vitronectin receptor (αvβ3), was used as target to study tumor angiogenesis in vivo, given that αvβ3 is highly expressed on activated endothelial and tumor cells." (PMID 31698751, 2019). "Similarly, ITGB3 and PLCB1 were also confirmed to facilitate HCC progression by enhancing the adhesion and proliferation of tumor cells." (PMID 31761783, 2019). "Our results suggested that cancer cells with silenced ITGB3 form fewer metastases and those that do appear are smaller than with control non-silenced tumour cells." (PMID 29383126, 2017). "By the efficient disassociation of ITGB3-TβRII signal-initiating complex, ICJ could suppress tumor metastasis while simultaneously had little influence on the activation of pro-apoptotic effects of TGF-beta." (PMID 27374079, 2016). "A significant difference in expression between tumours from survivors and tumours from deceased patients was detected for ITGB3 (p = 0.005), but not for the other proteins, CLU (p = 0.15), PRAME (p = 0.62), and CAPG (p = 0.24)." (PMID 19775429, 2009). "An increase in the betweenness centrality of a node/gene in tumor samples indicates that the gene lies on shorter paths connecting other genes, suggesting its role as a bridge in tumor-related PPIs, for instance, VCL, FLNA, TNS1, GATA3, and ITGB3, which may act as key connectors in tumor samples." (PMID 40626556, 2025). "ITGB3 could directly interact with proteins containing RGD (Arg-Gly-Asp) motif, such as fibronectin and vitronectin, which further play essential roles in tumor angiogenesis." (PMID 36130933, 2022). "Furthermore, the reduction of tumor-derived TNC could attenuate human umbilical vein endothelial cell (HUVEC) proliferation, migration and tube formation through ITGB3/FAK/Akt signaling pathway." (PMID 31036754, 2019). "Collectively, these data suggest that ITGB3 is translationally activated in hypoxia and regulates malignant features, including epithelial-mesenchymal transition and cell migration, through the TGF-β pathway, revealing a novel angle for the treatment of therapy-resistant hypoxic tumours." (PMID 29383126, 2017). "ITGB3 has been demonstrated to facilitate the H2O2/HOCl-mediated induction of invasive capacity, anoikis resistance, and extravasation of non-metastatic tumor cells by enabling TGF-β1 signaling." (PMID 39721996, 2024). "The expression level of integrin subunit beta 3 (ITGB3) tends to increase in tumor tissues, and HCC patients with high expression of ITGB3 also have poor overall survival (no statistical significance), which may be related to the limited sample size of the TCGA database." (PMID 41018265, 2025).